NINJ2 (ninjurin 2)
Diseases named in the same sentence as NINJ2 in open-access papers (continued):
Sharing a sentence is not in itself a finding about the gene and the disease.
lung carcinoma (1 paper, 2023). "In the following studies, a larger sample size is needed to verify the current results, and related experiments will be conducted to explore the underlying molecular mechanisms of MRPS30-DT and NINJ2 in the regulation of lung cancer." (PMID 36910850, 2023). "We further performed the stratified analyses by age, gender, smoking, and alcohol consumption to explore the effect of MRPS30-DT and NINJ2 variants on lung cancer risk." (PMID 36910850, 2023). "Nevertheless, NINJ2 (rs75750647 and rs10849390) increased the risk of lung cancer in people aged ≤59 years, while NINJ2 rs11610368 was correlated with a reduced risk of lung cancer in people aged >59 years." (PMID 36910850, 2023). "NINJ2 (rs75750647 and rs10849390) increased the risk of lung cancer in people aged ≤59 years, while NINJ2 rs11610368 was correlated with a reduced risk of lung cancer in people aged >59 years, non-drinkers, and non-smokers." (PMID 36910850, 2023). "We also revealed that the effect of MRPS30-DT and NINJ2 variants on the risk of lung cancer was dependent on age, gender, smoking, and drinking status." (PMID 36910850, 2023). "To conclude, we observed the relationship between genetic polymorphisms of MRPS30-DT and NINJ2 and the risk of lung cancer and proved that the effect of variants on lung cancer susceptibility was dependent on age, gender, smoking, and drinking status." (PMID 36910850, 2023). "In conclusion, this study first proved that MRPS30-DT and NINJ2 variants played important roles in affecting the susceptibility to lung cancer." (PMID 36910850, 2023). "In this study, we aimed to find out the effect of MRPS30-DT and NINJ2 variants on lung cancer risk." (PMID 36910850, 2023). "The effects of NINJ2 gene polymorphisms have been widely studied in stroke-related diseases and neurological disorders, while never in lung cancer." (PMID 36910850, 2023). "Thus, NINJ2 gene alterations may play an important role in lung disease, including lung cancer." (PMID 36910850, 2023).
myelodysplastic syndrome (1 paper, 2021). A clonal hematopoietic disorder characterized by dysplasia and ineffective hematopoiesis in one or more of the hematopoietic cell lines. "The epigenetic regulator Kdm5a44, a member of the gene group, often mutated in myelodysplastic syndrome (MDS), was found to be one of the genes within ~ ± 250 Kb from the RVI in the Ninj2 locus." (PMID 33674652, 2021).
ovarian serous cystadenocarcinoma (1 paper, 2024). A malignant serous cystic epithelial neoplasm arising from the ovary.
prediabetes (1 paper, 2025). "Compared to the control group, we detected 130 DMCs that were shared between the prediabetes and T2D groups, with LCLAT1, HLA-C, NINJ2, ZNF714, CNDP2, and HOOK2 among the top differentially methylated genes." (PMID 41373473, 2025).
cancer (8 papers, 2019 to 2026). A tumor composed of atypical neoplastic, often pleomorphic cells that invade other tissues. "Although NINJ2 has been implicated in various human diseases, including cancer, the specific mechanisms underlying its biological roles and potential oncogenic functions remain poorly understood." (PMID 40518514, 2025). "Although there were significant association between NINJ2 gene polymorphisms and nervous system disease, but few studies were conducted between NINJ2 gene polymorphisms and cancer." (PMID 33397383, 2021). "In this context, we confirmed that the proportion of NINJ2-positive cells in the ECF-R cancer cells (9.6 ± 1.3%) was higher than that in the parental cells (0.8 ± 0.09%)." (PMID 40518514, 2025). "Consistent with in vitro findings, NINJ2 K/D markedly reduced in tumor growth upon ECF exposure in ECF-R cancer cells." (PMID 40518514, 2025). "By measuring tumor volumes, we show that the xenografts-derived from NINJ2 knockout primary cancer cells (“KO-NINJ2”) grew significantly slower than the xenografts of control cancer cells (“Ctrl”)." (PMID 31597121, 2019). "Western blotting analyses confirmed significant NINJ2 protein upregulation in cancer tissues (representative tissues from five independent patients were shown)." (PMID 31597121, 2019). "While both NINJ1 and NINJ2 are found to be over-expressed in several types of cancers, it remains unclear whether they can be targeted for cancer treatment." (PMID 40136650, 2025). "NINJ2 K/D in ECF-R cancer cells enhanced chemosensitivity in vitro and in vivo." (PMID 40518514, 2025). "Thus, our study has laid a foundation for developing peptide-based strategies to target NINJ1 and NINJ2 for cancer therapy." (PMID 40136650, 2025). "Nonetheless, there was a little to what we could learn from the literature study on NINJ2: NINJ2 is a cell surface adhesion molecule upregulated in neurons and grail cells and several cancers." (PMID 35841085, 2022). "As shown, the NINJ2 shRNA led to dramatic inhibition of NINJ2 mRNA in the primary cancer cells." (PMID 31597121, 2019). "Consequently, the viability (MTT OD) and proliferation (BrdU ELISA OD) were decreased by NINJ2 shRNA in the primary cancer cells." (PMID 31597121, 2019). "Consistent with our results in cancer cells, the ECF-R tumor organoids had increased NINJ2 and CD44 mRNA levels compared with the parental tumor organoids." (PMID 40518514, 2025). "In four female carcinoma samples (COAD, HNSC, LUSC, and PAAD), three genes (AFAP1, NINJ2, and HOOK2) were commonly identified as classifiers, and the overexpression of the three genes was related to oncogenesis." (PMID 38929750, 2024). "The potential of these 4 molecules as a novel drug target also has been shown in a variety of studies: An accumulated knowledge on AGR2, PDE4D, NINJ2 and CDC25B have accelerated the drug discovery targeting these molecules in the other cancers." (PMID 35841085, 2022). "NINJ2 expression and potential function in CRC and other human cancers have not been studied." (PMID 31597121, 2019).
tumor (5 papers, 2019 to 2025). "To further understand how NINJ2 promotes tumor aggressiveness beyond chemoresistance, we investigated its potential involvement in mesenchymal transition." (PMID 40518514, 2025). "Furthermore, we generated tumor spheroids (enriched in CICs) to evaluate NINJ2 expression in spheroids." (PMID 40518514, 2025). "Recent evidence suggests that NINJ2 plays an oncogenic role in tumor progression." (PMID 40518514, 2025). "Next, we evaluated whether NINJ2 inhibition through multiple injections of polyvalent siRNA enhanced chemotherapeutic response in an ectopic tumor model." (PMID 40518514, 2025). "Importantly, p-Akt and p-Erk1/2 levels were also largely inhibited in sh-NINJ2- and KO-NINJ2-tumor tissues." (PMID 31597121, 2019). "Moreover, siRNA effectively downregulated NINJ2 expression in tumor tissues." (PMID 40518514, 2025). "We found that cell growth was inhibited by NINJ2-KO in MCF7 cells, as shown by the reduced numbers of colonies and tumor spheres." (PMID 38201656, 2024).
NINJ2 also shares sentences with these, for which no sentence is quoted: multiple sclerosis (3 papers); abdominal aortic aneurysm (1); acrocallosal syndrome (1); bipolar disorder (1); Borderline personality disorder (1); chronic kidney disease (1); diabetes (1); diabetic autonomic neuropathy (1); emphysema (1); hyperlipidemia (1); leukoaraiosis (1); mental disorder (1); nervous system disease (1); non-small cell lung carcinoma (1); pancreatic adenocarcinoma (1); pulmonary hypertension (1); schizophrenia (1); Thyroid adenoma (1).